GATA3 (GATA binding protein 3)
Diseases named in the same sentence as GATA3 in open-access papers (continued):
Sharing a sentence is not in itself a finding about the gene and the disease.
breast carcinoma (continued). "Both variants rs7714232 and rs16886272 associated with breast cancer, enhancer 119,861, and a binding site for transcription factor GATA3 are located in TAD 6450 whose boundaries are Chr5:56,010,000 – Chr5:56,140,000." (PMID 35176995, 2022). "These distinct clinical features suggest the differential impacts of GATA3 mutations on breast cancer cells." (PMID 35154280, 2022). "Our results suggest the common and different roles of GATA3 truncation mutations during luminal breast cancer development." (PMID 35154280, 2022). "These facts highlight the importance of the functional study of GATA3 and its mutations in breast cancer." (PMID 35154280, 2022). "Somatic mutation of GATA3 is associated with clinicopathological features and expression of TCGA in breast cancer patients." (PMID 35280773, 2022). "Our results provide evidence that MDM2 is a selected vulnerability in breast cancer with GATA3-mutation and/or loss of GATA3." (PMID 35440675, 2022). "GATA3 is frequently mutated in estrogen receptor (ER)-positive breast cancers and its deficiency defines a subset of patients with poor response to hormonal therapy and poor prognosis." (PMID 35440675, 2022). "Enhancer 119,861 is associated with breast cancer at a p-value of 2.4 × 10− 5 and GATA3 has a high disease association score of 5.9." (PMID 35176995, 2022). "GATA3 is one of the most frequently mutated genes in breast cancer, and its mutation affects breast cancer progression." (PMID 35993027, 2022). "GATA3 is mutated in >10% of breast cancers and directly impacts ESR1 enhancer accessibility, thereby altering binding potential and transcriptional targets in tumor cells." (PMID 36517508, 2022). "Studies on breast cancer cells showed that a breast cancer susceptibility gene 1 (BRCA1) complex with GATA-binding protein 3 (GATA3) reduced CXCL1 expression." (PMID 35054978, 2022). "Although GATA3 has been recognized as a prominent mutation in breast cancer, it still occurs at a lower frequency than both 1qG and 16qL in this subset." (PMID 35252434, 2022). "We next sought to determine if FOXA1 and GATA3 are causally involved in driving hypo-methylation in HCC1954 breast cancer cells." (PMID 35331302, 2022). "NGS revealed a pathogenic GATA3 frame-shift mutation, which occurs in approximately 15% of primary ER positive breast carcinomas." (PMID 36376842, 2022). "Worldwide breast cancer genome profiling keeps revealing GATA3 as one of the primary targets for somatic mutations in breast cancer." (PMID 35154280, 2022). "While patient genomic data suggests GATA3 mutations as cancer drivers, the functional consequences of GATA3 mutations in breast cancer are underexplored." (PMID 35154280, 2022). "This study provides the first genetic evidence demonstrating that loss-of-function of GATA3 directly induces basal-like breast cancer." (PMID 34976209, 2022). "Somatic mutations of GATA3 have been detected in ~15% of breast cancers and is one of the top three genes mutated in >10% of all breast cancers." (PMID 34976209, 2022). "GATA3 is mutated in 12–18% of primary and metastatic estrogen receptor (ER)-positive breast cancers, with predominantly frameshift mutations and mutations affecting splice sites." (PMID 35440675, 2022). "This study provides the first genetic evidence demonstrating that loss-of-function of GATA3 induces basal-like breast cancer." (PMID 34976209, 2022). "Our results suggest that in breast cancer cells, GATA3 loss-of-function (via genetic alterations or other mechanisms) activates the PI3K/Akt/mTOR pathway and leads to resistance to apoptosis." (PMID 35440675, 2022). "Based on the METABRIC cohort, among 1980 patient cases, 230 breast carcinomas harbored GATA3 mutations (∼11.6%)." (PMID 35154280, 2022).
breast carcinoma (continued). "Note the combined enrichment for FOXA1, ESR1, and GATA3 TFs close to the emCpGs; these 3 TFs have already been associated with DNA methylation patterns in estrogen receptor positive breast cancers." (PMID 35440061, 2022). "GATA3 is one of the most frequently mutated genes in breast cancer and has context-dependent tumor suppressive or oncogenic roles." (PMID 35846378, 2022). "Our results thus support MDM2 as a therapeutic target in the substantial fraction of ER-positive, GATA3-deficient breast cancer." (PMID 35440675, 2022). "Further investigation is essential for understanding the common and unique roles of GATA3 mutations in breast cancer." (PMID 35154280, 2022). "Relative to p18mt mammary tumors, p18mt;Gata3+/- tumors exhibited reduced expression of genes associated with luminal differentiation and enhanced expression of genes associated with basal differentiation." (PMID 34976209, 2022). "Haploid loss of Gata3 by heterozygous germline deletion of Gata3, although insufficient to induce mammary tumors alone, changes the properties of mammary tumors induced by p18 deficiency, resulting in their malignant and luminal-to-basal-like transformation." (PMID 34976209, 2022). "p18 deficiency rescues the proliferative defect caused by haploid loss of Gata3 and induces luminal type mammary tumors." (PMID 34976209, 2022). "This is consistent with recent work showing that GATA3 mutations in breast cancer can be segregated by their effect on the function of the GATA3 protein into subsets consistent with those identified as divergent above." (PMID 33957863, 2021). "In contrast, increased ERα and GATA3 expression were associated with a higher overall survival rate in patients with breast cancer." (PMID 34026424, 2021). "A recent genomic analysis of human breast cancer has revealed a high-frequency of mutation in GATA3 in luminal tumors." (PMID 34301206, 2021). "Mutation of GATA3 is frequently observed in breast cancer, and its expression is lost in mouse models of breast cancer and in upper tract urothelial carcinoma." (PMID 34595169, 2021). "Other well-known breast cancer associated genes that were highly expressed in both cell systems included GATA3, GNAS, FASN and NCOA3." (PMID 34680485, 2021). "The analysis of clinical factors in relationship with the GATA3 somatic mutations reported in TCGA-BRCA project revealed that GATA3 mutations were associated with several clinical features and pathological subtypes of breast cancer." (PMID 33462316, 2021). "By using these mutant mice along with human BRCA1 deficient as well as proficient breast cancer tissues and cells, we investigated and compared the role of Brca1 and Gata3 loss in the activation of EMT in breast cancers." (PMID 34373738, 2021). "In brief, the altered expression pattern of FOXM1/GATA3/FOXA1/ESR1-associated lncRNAs in breast cancer suggests future assessment of the functional role of these genes in the development of breast neoplasms." (PMID 34094972, 2021). "This study was conducted to evaluate the association of GATA3 somatic mutations with tumor features, survival, and expression profiles in breast cancer." (PMID 33462316, 2021). "In the present study, we demonstrated that BRCA1 mutation is associated with GATA3 promoter hypermethylation and reduced GATA3 expression in human breast cancer samples." (PMID 34373738, 2021). "GATA3 is the third most mutated gene in luminal breast cancers with a prevalence of approximately 14% and 15% in luminal A and B tumors, respectively (cbioportal.org, TCGA Firehose Legacy dataset)." (PMID 34831189, 2021). "In particular, GATA3 expression was linked to a favorable prognosis in lung adenocarcinoma, urothelial cancer, and breast cancer." (PMID 34573939, 2021).
breast carcinoma (continued). "The association of GATA3 with human cancers has been reported in a large amount of human cancers, such as liver cancer, breast cancers, and endometrial carcinomas." (PMID 34399777, 2021). "These traits associated with invasiveness and metastasis in many cancers have been recently linked to increased GATA2 as well as GATA3 expression after induced hypomethylation by hypoxia or hypomethylating agents in ovarian and breast cancer." (PMID 34831278, 2021). "We found that Gata3 deficiency in mice induced poorly-differentiated mammary tumors with the activation of EMT and promoted tumor initiating and metastatic potential." (PMID 34373738, 2021). "We followed tumor development in these mice and found that 50% (n = 34) of p18mt;Gata3+/- and 30% (n = 27) of p18mt mice developed mammary tumors between 8-20 months, indicating that haploid loss of Gata3 in p18 mutant mice accelerates mammary tumorigenesis." (PMID 34373738, 2021). "Together, these results indicate that haploid loss of Gata3 induces poorly-differentiated mammary tumors with the activation of EMT." (PMID 34373738, 2021). "In the present study, we determined and compared the EMT phenotype in mammary tumors developed in mice deficient for Brca1 or Gata3 under the same p18 deficient background." (PMID 34373738, 2021). "We demonstrated that Gata3 deficient mammary tumors phenocopy Brca1 deficient tumors in induction of EMT, and that reconstitution of Gata3 in Brca1-deficient tumor cells activates MET suppressing tumor initiation and metastasis." (PMID 34373738, 2021). "We discovered that Gata3 deficiency activates EMT in the induction of mammary tumors and promotes tumor initiation as well as the metastatic potential of cancer cells, which phenocopy Brca1 deficient tumors and tumor cells." (PMID 34373738, 2021). "We found that Gata3 deficient mammary tumors phenocopied Brca1 deficient tumors in the induction of EMT and promotion of tumorigenesis and progression." (PMID 34373738, 2021). "To determine if Gata3 affects Brca1 deficient mammary tumor metastasis, we transplanted Empty- and Gata3-expressing p18-/-; Brca1MGKO tumor cells into MFPs of NSG mice." (PMID 34373738, 2021). "Together, these results indicate that Gata3 deficiency in mammary tumor cells promotes the potential for tumor initiation and metastasis." (PMID 34373738, 2021). "We discovered that Gata3 deficiency induces poorly-differentiated mammary tumors with the activation of EMT and promotes the potential for tumor initiation and metastasis." (PMID 34373738, 2021). "Gata3 deficient mammary tumors phenocopied Brca1 deficient tumors in the induction of EMT under the same genetic background." (PMID 34373738, 2021). "In this light, we believe that Moonlight was not only able to detect the oncogene behavior of GATA3 in breast cancer with precision but was also able to elucidate the underlying mechanism and mutation sites." (PMID 31900418, 2020). "Numerous reports have detailed that loss of GATA3 expression is associated with a propensity for tumour metastasis, with mechanistic studies suggesting that GATA3 inhibits breast cancer metastasis by reversing epithelial-mesenchymal transition (EMT)." (PMID 33298139, 2020). "Among these, ER and GATA3 regulation is directly associated with breast cancer, and NF-кB regulation is also thought to influence the cell growth of various cancers, in addition to its main role in the control of immune processes." (PMID 32847068, 2020). "NRAS Q61K missense mutation in the ectodermal group mainly occurs in the patients with skin cancer, while splice acceptor GATA3 X309_splice mutations only present in the breast cancer cases derived from ectoderm." (PMID 33308219, 2020). "In particular, we observed that GATA3 showed the highest mutation rate in breast-cancer samples in splice-site and frameshift insertions." (PMID 31900418, 2020).
breast carcinoma (continued). "GATA3 levels are also inversely associated with the metastatic capability of various human breast cancer cell lines." (PMID 32934779, 2020). "Although GATA3 is included in the QIAseq Human Breast Cancer Panel, we were unable to detect this mutation by web-portal analysis because of its low variant frequency." (PMID 33004031, 2020). "This is specific for breast cancer (BC), where GATA3 is mutated in around 11% of cases and shows a characteristic mutational pattern, different from other tumor types." (PMID 32587399, 2020). "A recent study has shown that the insulin-dependent increase in the expression of T-bet in breast tumors is associated with a subsequent decrease in the expression of GATA3, followed by resistance to hormonal therapy in human ER+ breast cancer." (PMID 32225066, 2020). "Research has revealed that GATA3 can regulate a number of genes associated with breast to lung metastasis, as well as impede breast cancer metastasis through the inhibition of EMT." (PMID 33298139, 2020). "After a second surgery, mutation analysis of her bilateral breast cancer was performed in a clinical study, which revealed that her metachronous bilateral breast tumors had the same GATA3 and CSMD1 mutations." (PMID 32833091, 2020). "Studies have shown that GATA3 is necessary for luminal epithelial cell differentiation and the gene is often mutated in human breast cancer." (PMID 31408468, 2019). "Next, we investigated the role played by GATA3 and UTX in breast cancer invasion and metastasis: we performed GATA3/UTX loss-of-function and gain-of-function experiments and examined the expression levels of epithelial and mesenchymal markers." (PMID 31685800, 2019). "GATA3 has been implicated in breast tumorigenesis and its highest expression was observed in the luminal subtype of breast cancer." (PMID 31408468, 2019). "Genomic analyses reveal a high frequency target mutation of GATA3 in breast cancer, melanomas, clear cell sarcoma and poor prognosis." (PMID 31024232, 2019). "Our analysis corroborates the concept that mutations in GATA3 are associated with a better outcome in ER+ breast cancer patients." (PMID 30691046, 2019). "In breast cancer, somatic mutations in GATA3 are common with roughly half the reported mutations resulting in a C-terminal frameshift with stop-loss and extension." (PMID 31238969, 2019). "There was also a report that showed that high GATA3 expression was associated with an unfavorable prognosis in breast cancer patients." (PMID 30872657, 2019). "Nearly 10% of human breast cancers are associated with GATA3 mutations in the C-terminal zinc finger of ZNII." (PMID 31614829, 2019). "In breast cancer TH2 cells increase the risk of metastasis to sentinel lymph nodes by the expression of GATA binding protein 3 (GATA-3)." (PMID 31579438, 2019). "Both clinical and experimental lines of evidence link mutations in GATA3 directly to breast cancer development and progression." (PMID 31304632, 2019). "In breast cancer GATA3 is known to be frequently mutated, but the function of these mutations is unclear." (PMID 29535312, 2018). "In the present study, we report that Notch3 expression positively correlates with that of GATA-3, and both are associated with estrogen receptor-α (ERα) expression in breast cancer cells." (PMID 30100605, 2018). "In a murine luminal breast cancer model, the loss of Gata3 resulted in tumour progression and tumour dissemination." (PMID 30463912, 2018). "With this, we show divergent clinical correlations of the two ERα pioneer factors FOXA1 and GATA3 in metastatic breast cancer, where endocrine therapy resistance was associated with decreased FOXA1 levels in pleural metastases." (PMID 29972720, 2018).
breast carcinoma (continued). "Utilizing genome editing, we develop a model to study the molecular outcomes of frame-shift mutations in the second zinc finger of GATA3 in breast cancer." (PMID 29535312, 2018). "Our investigation of the regulatory mechanism of Notch3 and GATA-3 found that both were positively associated with ER expression in breast cancers." (PMID 30100605, 2018). "Unsurprisingly, decrease or loss of expression of GATA-3 is associated with pathogenesis, hormone receptor negativity, and an unfavorable prognosis for breast cancer patients in the clinic." (PMID 30100605, 2018). "In breast cancer patients, high GATA-3 expression is associated with higher Notch3 expression and lower lymph node metastasis, especially for hormone receptor (HR) positive cancers." (PMID 30100605, 2018). "Its crucial role in the mammary gland is supported by the detection of GATA3 mutations in around 10% of human breast cancers." (PMID 30463912, 2018). "Here, the authors utilise CRISPR-Cas9 to model frame-shift mutations in zinc finger 2 of GATA3, highlighting that GATA3 mutation can have gain- or loss-of function effects in breast cancer." (PMID 29535312, 2018). "Notch3 expression either in nuclear or in cytoplama was strongly associated with that of GATA-3 in breast cancer tissue samples (Pearson r = 0.408, P = 0.001)." (PMID 30100605, 2018). "Pooled RRs were used to illustrate the association between GATA3 protein expression level and pathological features of breast cancer." (PMID 28394898, 2017). "In human cancers, frequent loss-of-function of GATA3 alteration and copy number deletions were observed in breast cancer and T cell leukemia/lymphoma recently." (PMID 28415601, 2017). "In conclusion, this meta-analysis revealed that high expression of GATA3 in breast cancer is associated with improved TTP." (PMID 28394898, 2017). "It is possible that a different subset of genes is affected by GATA3 mutation in luminal progenitor cells than in established breast cancer cells." (PMID 29262572, 2017). "The biological relevance of the genes affected by GATA3 mutation in our study will require further analysis, but several of them have plausible roles in breast cancer." (PMID 29262572, 2017). "We also observed concordant differential expression for a subset of these genes according to GATA3 mutation status in primary ER+ breast cancers from the TCGA dataset." (PMID 29262572, 2017). "Gata3, the expression of which is strongly associated with ERα in breast cancer, is considered a prognostic marker for less aggressive breast cancer and associates with favorable outcome." (PMID 29051494, 2017). "High expression of GATA3 was associated with better TTP of breast cancer (pooled HR = 0.671; 95% CI = 0.475–0.947; P = 0.023)." (PMID 28394898, 2017). "In this study, we have used gene editing to examine the functional consequences of a recurrent GATA3 truncating mutation in two ER+ breast cancer cell lines, including MCF-7, where the mutation naturally occurs." (PMID 29262572, 2017). "In order to study the functional consequences of GATA3 mutations in a human breast cancer system, we utilized the MCF-7 cell line, widely used as a representative model for ER+, luminal-type breast cancer." (PMID 29262572, 2017). "It has long been recognized that GATA3 mutations occur in the better-prognosis luminal subtypes of breast cancer." (PMID 29262572, 2017). "The TCGA dataset contains 594 primary ER+ breast cancers with RNAseq and mutation data, of which 84 (14%) have GATA3 mutations." (PMID 29262572, 2017). "Human patient data have shown that high Gata3 expression, a feature of luminal subtype breast cancers, is associated with a better prognosis." (PMID 29262572, 2017). "Our microarray data identifies a set of genes which are concordantly affected by GATA3 mutation in two ER+ breast cancer cell lines." (PMID 29262572, 2017).